AVPR1B (arginine vasopressin receptor 1B)
Description:
Receptor for arginine vasopressin. The activity of this receptor is mediated by G proteins which activate a phosphatidyl-inositol-calcium second messenger system. (Microbial infection) During SARS coronavirus-2/SARS-CoV-2 infection, may recognize and internalize the complex formed by AVP/Arg-vasopressin, SARS-CoV-2 spike protein and secreted ACE2 through DNM2/dynamin 2-dependent endocytosis.
Synonyms: V1bR; AVPR3; VPR3
Tractability: Small molecule: a drug acting on it is in phase 2 or 3 trials; a high-quality ligand is known; it belongs to a druggable protein family. Antibody: UniProt places it where antibodies can reach, with high confidence; its Gene Ontology location is reachable by antibodies, with high confidence; UniProt predicts a signal peptide or a membrane-spanning region. PROTAC: a small molecule that binds it is known. Other modalities: an approved drug acts on it.
Target class: Family A G protein-coupled receptor; Vasopressin and oxytocin receptor; Short peptide receptor (family A GPCR); Membrane receptor; Peptide receptor (family A GPCR)
Chemical probes: CHEMBL1765669, Vasopressin antagonist 1867
Gene: Protein-coding gene on chromosome 1 (206,106,936 to 206,117,699, reverse strand). Ensembl gene ENSG00000198049.
Subcellular location: Cell membrane
Pathways (Reactome):
Signal Transduction: G alpha (q) signalling events; Vasopressin-like receptors
Disease: Defective AVP does not bind AVPR1A,B and causes neurohypophyseal diabetes insipidus (NDI)
Gene Ontology:
Molecular function: protein binding; vasopressin receptor activity; protein kinase C binding; G protein-coupled peptide receptor activity; G protein-coupled receptor activity
Biological process: G protein-coupled receptor signaling pathway; phospholipase C-activating G protein-coupled receptor signaling pathway; positive regulation of arachidonate secretion; positive regulation of inositol phosphate biosynthetic process; positive regulation of MAPK cascade; regulation of cell population proliferation; symbiont entry into host cell; cellular response to hormone stimulus; positive regulation of cytosolic calcium ion concentration; positive regulation of vasoconstriction; regulation of systemic arterial blood pressure by vasopressin; transport across blood-brain barrier; regulation of blood pressure
Cellular component: Golgi apparatus; plasma membrane; endosome; membrane
Genetic constraint (gnomAD): Loss-of-function variants: 25 observed, 29.24 expected, observed/expected ratio (o/e) 0.85, 90% interval 0.62 to 1.19. The upper end of that interval is the gene's LOEUF score, 1.19, which puts it in group 5 of 6, group 1 being the genes least tolerant of losing a copy. Missense variants: 595 observed, 583.22 expected, observed/expected ratio (o/e) 1.02, 90% interval 0.95 to 1.09. Synonymous variants: 248 observed, 253.73 expected, observed/expected ratio (o/e) 0.98, 90% interval 0.88 to 1.09.
Homologues: Orthologues: chimpanzee AVPR1B (99% identical), macaque AVPR1B (96% identical), pig AVPR1B (84% identical), rabbit AVPR1B (84% identical), dog AVPR1B (82% identical), rat Avpr1b (81% identical), guinea pig AVPR1B (81% identical), mouse Avpr1b (81% identical), tropical clawed frog avpr1b (54% identical), Drosophila melanogaster CCAP-R (28% identical). Paralogues in human: OXTR (46% identical), AVPR1A (45% identical), AVPR2 (36% identical), GPR150 (22% identical), CCKBR (21% identical), CCKAR (21% identical), GALR3 (19% identical), NPFFR2 (18% identical), GNRHR (18% identical), HCRTR2 (18% identical), NPFFR1 (17% identical), GALR1 (17% identical), and 4 more.
Diseases named in the same sentence as AVPR1B in open-access papers:
AVPR1B is named in the same sentence as 48 diseases in open-access papers, as found by Europe PMC text mining. Sharing a sentence is not in itself a finding about the gene and the disease. The quoted sentences say what the papers report.
depression (21 papers, 2009 to 2025). "Human studies including our results have linked AVPR1B to disorders with social components including bipolar type I, depression, autistic traits as measured by EQ, childhood aggression, COMD, suicidal attempts, prosociality, and emotional empathy." (PMID 27920663, 2016). "Intriguingly, both the clock gene and the AVPR1b gene are associated with depression and bipolar disorder." (PMID 25309987, 2014). "Nonetheless, it is worth mentioning that the two reports associating AVPR1B variants to depression/mood disorders identified the same major haplotype as being either protective or predisposing in different population of European descent." (PMID 19486526, 2009). "These explanations have been regarded as possibly supporting an adaptive origin for depression/low mood in humans, a condition which has been associated to polymorphisms in AVPR1B." (PMID 19486526, 2009). "Likewise, treatment with an Avpr1b antagonist has been found to reduce anxiety-like and depressive-like behaviors in rodents, and SNPs of the Avpr1b are associated with anxiety and depression in humans." (PMID 29085277, 2017). "On the other hand, genetic associations with lifetime diagnoses of depression and anxiety in SA or G × E interactions between AVPR1B variants and SLEs (childhood/adolescence/adulthood physical assault or sexual assault, and high lifetime SLEs) were not significant." (PMID 27721799, 2016). "Furthermore, polymorphisms in the Avpr1b gene have been associated with depression, childhood-onset mood disorder and attention-deficit hyperactivity disorder." (PMID 20828336, 2011). "Interestingly, a selective V1b antagonist produces anxiolytic- and antidepressant-like effects in rodents and in humans AVPR1B variants have been associated with recurrent major depression, early-onset mood disorders and panic disorder." (PMID 19486526, 2009). "Studies on AVPR1B antagonists have yielded favorable results such as alleviation of anxiety and depression in animal and human models." (PMID 30719038, 2019). "The behavioural implications of Avp, acting via the Avpr1b, in aggression and stress, and the integral connection between stress, anxiety and depression make the Avpr1b an attractive target for pharmacological intervention." (PMID 20828336, 2011). "We also observed that additional genes had annotated transcripts in the 3 macaque species with no identified ortholog in humans; these included AVPR1B (NM_0 012 46222.1), the mutations of which correlate with anxiety, depression, and panic disorder in humans." (PMID 32649757, 2020). "Because prosociality may serve as a coping strategy for reducing depression and stress, we hypothesized that variations in the AVPR1b gene are related to prosociality and that this relation might be modulated by the clock gene." (PMID 25309987, 2014). "Evidence suggests that the AVPR1b gene is closely related to anxiety and depression." (PMID 25309987, 2014). "Therefore, it is not surprising that SNVs of the AVPR1B gene are increasingly singled out in GWAS studies as candidates for assessing the risk of the development of major depression and other stress-related psychopathologies." (PMID 38002996, 2023). "Experiments on Avpr1b-/-mice suggest that social memory is regulated by the V1bR located in the CA2 region of the hippocampus and that the blockade of V1bR induces anxiolytic actions in various models of depression." (PMID 35207180, 2022). "In contrast, no major changes in anxiety-like or depression-like behaviours are observed in Avpr1b KO animals." (PMID 20828336, 2011).
Anxiety (12 papers, 2011 to 2023). Intense feelings of nervousness, tension, or panic often arise in response to interpersonal stresses. "Of these areas, both the basolateral and medial amygdala have been implicated specifically in the mediation of anxiety by Avpr1b, with evidence for additional modulation via the Oxtr, while the Avpr1b in the LS is suspected to be involved in depressive states." (PMID 29085277, 2017). "Additionally, associations between anxiety and panic disorders and AVPR1B rs28632197 have been observed." (PMID 27920663, 2016). "Finally, we assessed the moderating influence of candidate genes whose level of methylation is associated with the Nr3c1 genotype on anxiety-like behavior: Ank3, Avp, Avpr1a, Avpr1b, Bdnf, Cacna1c, Cyp11b1, Cyp11b2, Fkbp5, Hsd11b1, Igf2, Morc1, Nr3c1, Oxt, Oxtr, Pclo, Slc6a4." (PMID 30655507, 2019). "Overall, an increased Avp and Avpr1b expression is in accordance with our previous result that KP-13 induces anxiety-like behavior in rats." (PMID 37760887, 2023). "On the other hand, there was a significant increase of general anxiety in Avpr1b KO females, as evidenced consistently by the three measurements." (PMID 35017259, 2022). "Given that preclinical work in animal models suggests that antagonism of Avpr1b with SSR149415 can reduce anxiety-like and depressive-like behaviors, SSR149415 was approved for clinical trials." (PMID 29085277, 2017). "This latter study hints at a possible point of intersection between the peripheral effects of the Avpr1b and those within the brain with regards to anxiety and mood." (PMID 29085277, 2017). "Resident-intruder aggression in Avpr1b KO mice was decreased without co-occurring deficits in predatory aggression or anxiety and remained deficient in a KO on a more outbred strain of mice." (PMID 31787886, 2019). "To determine the role that plasticity may have in Avpr1b neuron-dependent behaviors, we selectively inactivated NMDA receptors in Avpr1b neurons through genetic removal of the obligatory Grin1 gene, and assessed aggression, memory and anxiety-like behaviors." (PMID 31787886, 2019). "Even in Avpr1b−/− mice in which Avpr1b function in the CA2 region of the hippocampus is partially restored, no significant genotypic differences in anxiety-like behaviors are observed." (PMID 29085277, 2017).
Hypoglycemia (6 papers, 2009 to 2024). A decreased concentration of glucose in the blood. "We have previously demonstrated the prominence of AVP/Avpr1b in the plasma ACTH and CORT responses to acute insulin-induced hypoglycaemia stress in mice." (PMID 20846299, 2010). "Despite the drastic reduction in plasma glucagon by pharmacological antagonism of the V1bR or genetic KO of Avpr1b, the depth of hypoglycemia was not affected." (PMID 34787082, 2021).
diabetes (5 papers, 2013 to 2024). "It has also been reported that the allele of rs35810727 AVPR1B gene is associated with elevated body mass index, and that the human subjects carrying this variance of the AVPR1B gene are more prone to develop obesity and diabetes mellitus." (PMID 38279313, 2024).
autism (4 papers, 2016 to 2024). Persistent deficits in social interaction and communication and interaction as well as a markedly restricted repertoire of activity and interest as well as repetitive patterns of behavior. "Genetic variants of AVPR1B are linked to psychiatric disorders commonly diagnosed in childhood, including autism, attention deficit hyperactivity disorder (ADHD), and mood disorders." (PMID 38702611, 2024).
ACTHomas (3 papers, 2017 to 2021). "In corticotroph adenomas, pituitary-specific hormone gene expression of arginine vasopressin receptor 1B (AVPR1B) is observed to express higher in SCAs than in CDs." (PMID 34885244, 2021). "Silent corticotropinomas also overexpress the AVPR1b and the CRH-R1 genes, similar to functioning CT." (PMID 28692683, 2017). "In addition to the impaired glucocorticoid negative feedback, ACTHomas exhibits increased or aberrant expression of AVPR1b or AVPR2, which is associated with a paradoxical response to DDAVP." (PMID 33266265, 2020). "As normal corticotrophs express lower levels of AVPR1b, and intra-venous DDAVP injection does not stimulate ACTH secretion in patients who do not have ACTHomas, AVPR1b or AVPR2 has been shown to express abundantly in ACTHomas." (PMID 33266265, 2020).
mood disorder (3 papers, 2009 to 2024). A cognitive disorder a disturbance in which the person's mood is hypothesized to be the main underlying feature. "In humans, variations in the Avpr1b gene have been found to be associated with mood disorders." (PMID 29085277, 2017). "In a study of Hungarian children diagnosed with a mood disorder prior to 15 years of age, genetic markers in the Avpr1b gene (rs28373064, rs35369693, and rs33985287) are directly associated with affective status in children." (PMID 29085277, 2017).
panic disorder (3 papers, 2016 to 2023). An anxiety disorder characterized by multiple unexpected panic attacks with persistent concern of recurring attacks. "Other positively selected variants of the AVPR1B gene that we found are known to be associated with side effects of vasopressin, panic disorders, aggression in children, and autism spectrum disorders (ASD)." (PMID 38002996, 2023). "Two SNP pairs, AVPR1B rs28632197—CRHR1 rs878886 and AVPR1B rs28632197—CRHR1 rs187631, were also found to be significantly associated with panic disorder." (PMID 27920663, 2016). "Keck and colleagues compared individuals with panic disorder with matched controls and found nominal associations with panic disorder and AVPR1B, including rs28632197 (p = 0.046), in their main sample (not significant in their replication sample or the combined sample)." (PMID 27920663, 2016).
adenoma (2 papers, 2013 to 2020). A neoplasm arising from the epithelium. "Expression of mRNA of vasopressin receptors (AVPR1A, AVPR2, AVPR1B) was studied in a panel of adrenocortical tissues, consisting of AIMAH, normal adrenals, ACTH-dependent hyperplasias, adenomas and carcinomas." (PMID 24034279, 2013).
autism spectrum disorder (2 papers, 2021 to 2023). A spectrum of developmental disorders that includes autism, and Asperger syndrome. "AVPR1B has been associated with autism spectrum disorders and is a receptor involved in the AVP-mediated activation of the hypothalamic-pituitary-adrenal-axis." (PMID 33834688, 2021).
Obesity (2 papers, 2016 to 2024). Accumulation of substantial excess body fat. "Here, we aim to investigate if the genetic variation of the human AVP receptor 1b gene (AVPR1B) is associated with measures of obesity and DM." (PMID 26503846, 2016). "Here, we hypothesized that genetic variance of the human V1b receptor gene (AVPR1B) is associated with measures of obesity and with DM." (PMID 26503846, 2016). "Four tag single nucleotide polymorphisms (SNPs: rs35810727, rs28373064, rs35439639, rs35608965) of AVPR1B were genotyped in the cardiovascular cohort (n=6103) of MDC (MDC-CC) and associated with measures of obesity and DM." (PMID 26503846, 2016). "As we previously found an association between elevated copeptin and measures of obesity in the MDC-CC, we investigated the association between AVPR1B tag SNPs and the copeptin level in the MDC-CC." (PMID 26503846, 2016). "Regarding the previous associations between elevated copeptin and measures of obesity in this cohort, we did not know what to expect regarding the copeptin level among subjects carrying the major allele of AVPR1B, i.e., elevated or decreased copeptin level." (PMID 26503846, 2016). "None of the other AVPR1B tag SNPs (rs28373064, rs35439639, rs35608965) was significantly associated with any measures of obesity." (PMID 26503846, 2016). "The genetical variation in AVPR1B seems to have a modest effect on BMI, waist circumference and overweight, and therefore we believe that the lack of association for obesity and abdominal obesity are explained by lower power due to lower numbers of these dichotomized traits." (PMID 26503846, 2016). "Our present data, linking elevated BMI and overweight to AVPR1B tag SNP rs35810727, are in line with our previous findings that imbalance of the AVP system, using copeptin as a proxy for AVP, is associated with measures of obesity both cross-sectionally and at follow-up." (PMID 26503846, 2016).
colorectal cancer (1 paper, 2012). A primary or metastatic malignant neoplasm that affects the colon or rectum. "In this study, we hypothesized that genetic variants located within the SLC6A4, BDNF, and AVPR1B genes are associated with prognosis in colorectal cancer patients." (PMID 22911682, 2012). "Consequently, in the present study, we have aimed to test the associations of five genetic variations in stress response genes (SLC6A4, BDNF, and AVPR1B) with clinical outcomes in a population-based cohort of 280 colorectal cancer patients from Newfoundland and Labrador (NL)." (PMID 22911682, 2012).
Hypertension (1 paper, 2013). The presence of chronic increased pressure in the systemic arterial system. "A study of the role of AVP for the development of hypertension after constriction of the abdominal aorta proximal to the renal arteries concluded that AVP plays an important role in the development of hypertension and that the action is mediated via the vascular AVP-receptor (AVPR1B)." (PMID 24174980, 2013). "Based on the downregulation of AVPR1B and ACE and the upregulation of DRD5, DG treatment may be involved in the rennin-angiotensin system and the receptor-mediated improvement of hypertension." (PMID 24174980, 2013).
memory impairment (1 paper, 2021). "The CA2 is highly expressed with the vasopressin 1b (Avpr1b) receptor, and the knockout of Avpr1b results in social memory impairment, whereas targeted activation of CA2 Avpr 1b during the acquisition period could enhance social memory, demonstrating their association." (PMID 34385906, 2021).
somatotropinoma (1 paper, 2018). "In contrast, other receptors subtypes involved in the function of different pituitary cell types, such as gonadotropin-releasing hormone receptor (GnRHR), corticotropin-releasing hormone receptor (CRHR1) or vasopressin receptor (AVPR1b) were not noticeably expressed in somatotropinoma samples." (PMID 29670116, 2018).
cancer (4 papers, 2013 to 2024). A tumor composed of atypical neoplastic, often pleomorphic cells that invade other tissues. "Lastly, AVPR1B is associated to desmopressin which may impair metastasis of cancer cells." (PMID 24379827, 2013).
psychiatric disorder (3 papers, 2009 to 2024). A disorder characterized by behavioral and/or psychological abnormalities, often accompanied by physical symptoms. "We then examined methylation in a shortlist of genes that were previously associated with early life stress and psychiatric disorders as well as placental functioning: Ank3, Avp, Avpr1a, Avpr1b, Bdnf, Cacna1c, Cyp11b1, Cyp11b2, Fkbp5, Hsd11b1, Igf2, Morc1, Nr3c1, Oxt, Oxtr, Pclo, Slc6a4." (PMID 30655507, 2019). "Analysis of AVPR1B evolutionary history in humans might fit both these aims since the gene has been involved in complex behavioral traits in other mammals and it has been associated with psychiatric diseases." (PMID 19486526, 2009).
AVPR1B also shares sentences with these, for which no sentence is quoted: metabolic syndrome (6 papers); anxiety disorder (3); generalized anxiety disorder (3); bipolar disorder (2); schizophrenia (2); tumor (2); Abdominal obesity (1); adenocarcinoma (1); atherosclerosis (1); attention deficit-hyperactivity disorder (1); cerebral (1); cognitive disorder (1); Cushing syndrome (1); dilated cardiomyopathy (1); epilepsy (1); heart failure (1); hypercortisolism (1); hypertrophic cardiomyopathy (1); inflammatory bowel disease (1); Insulin resistance (1); major depressive episode (1); male infertility (1); melancholic depression (1); migraine (1); motion sickness (1); osteoporosis (1); Parkinson’s (1); rheumatoid arthritis (1); squamous cell carcinoma (1); stress-related disorder (1).
A further 1 disease shares a sentence with AVPR1B in 1 paper.